KRT8 (keratin 8)
Diseases named in the same sentence as KRT8 in open-access papers (continued):
Sharing a sentence is not in itself a finding about the gene and the disease.
tumor (continued). "The high expression of tumor-related genes (EPCAM, CD24, CDH1, ELF3, KRT18, KRT19, KRT8, and MUC1) in groups 10 and 11 suggests that cells in these groups are tumor cells." (PMID 38693422, 2024). "We noted a relative upregulation of specific luminal markers, KRT8 and KRT7, as well as distinctive expression of basal-like marker KRT81 in the migratory tumor subtype." (PMID 38892065, 2024). "ASCL1, a marker of emerging NE cells, was detected at 4–6 weeks, appearing as EGFP+;KRT8+;ASCL1+ tumor cell clusters." (PMID 39394434, 2024). "GFP expression was almost exclusive to alveolar regions and tumours, the latter of which were almost entirely GFP+ as well as KRT8+ and KAC marker-positive (CLDN4+CAVIN3+)." (PMID 38418883, 2024). "Subsequently, utilizing machine learning techniques, we constructed the PIS model, comprising marker genes of CKS1B+ tumours (RHOV, ANLN, DEAR, PSMB7, KRT8, LDHA)." (PMID 38946232, 2024). "CK8 (KRT8), CK18 (KRT18), and EPCAM were expressed differentially (upregulated) in TRG5 tumours, but undetectable in the regressed lesion." (PMID 38630793, 2024). "In contrast, 16 out of 17 lung metastases from Krt8-CreERT/Rosa26-mTmG /MMTV-PyMT mice express GFP, indicating that the metastatic colony is seeded from a tumor cell of a luminal lineage." (PMID 36859337, 2023). "Both PD-L1-negative and PD-L1-positive patients showed clusters of tumor cells expressing KRT7, KRT8, and KRT18." (PMID 36674951, 2023). "When restricting disseminated tumor cell detection to keratins KRT7 and KRT8, the prognostic information was substantially stronger (p = 1 × 10–6; HR = 22, and p = 2 × 10–5; HR = 7.7, respectively)." (PMID 35659265, 2022). "The main cell clusters included T cells (CD3E and CD3D), B cells (CD19), natural killer cells (NCAM1, FCGR3A and KLRD1), myeloid cells (CD86 and CD163) and tumor cells (EPCAM, KRT8 and KRT18)." (PMID 36497182, 2022). "On the other hand, in domain 4, we observed upregulation of KRT8, AQP3, KLHDC7B and CDH1, which tend to exhibit stronger tumor progression and metastasis, and high expression of genes NUPR1 and DBI associated with chemotherapy resistance." (PMID 36250636, 2022). "The results show that KRT8, PSMD2, TRIM28, and UBE2V2 are significantly overexpressed in tumor tissues, while the expression level of FBXO9, MYLIP, and RNF180 is significantly reduced in LUAD (p < 0.05)." (PMID 35711913, 2022). "Keratin 8 (KRT8), a major component of the intermediate filament cytoskeleton, promotes tumor progression and metastasis of various cancers." (PMID 34899682, 2021). "A few differentially expressed genes between the PitNET subtypes also correlate with tumor size (CACNA2D2, CGA, KRT8, RALGAPA2) suggesting a potential role in tumor growth." (PMID 34758873, 2021). "Interestingly, FC2 displayed the highest correlation with epithelial cells and showed specific expression of tumor epithelial markers KRT8, KRT10, and KRT18, as well as the EMT markers SNAI1 and SNAI2, suggesting that FC2 may have the tumor‐like aggressive potential." (PMID 34459128, 2021). "For VPS35 the correlation between corrected spots per well VPS35-specific IFN-g T cells and tumor size was R2 was 0.56 (p = 0.03), for APRC2 the R2 was 0.78 (p = 0.02), for SERBP1 the R2 was 0.55 (p = 0.03), and for KRT8 the R2 was 0.64 (p = 0.02)." (PMID 33976232, 2021). "The overexpression of Cytokeratin 8 (CK8), together with its heterodimeric partners CK18 and CK19, on the surface of tumor cells has been demonstrated to inhibit MHC I interactions with TCRs on CD8+ CTLs." (PMID 31980023, 2020). "We provide evidence that KRT8 is significantly elevated in a subset of patients with various types of cancers, including in ATC patient tumors and tumor-derived ATC PDX cell lines." (PMID 29443941, 2018). "As expected, KRT8 and KRT17/19 were localized to ovarian surface epithelia of control and TGFBR1-CAAcre mice, with low to undetectable expression in the tumor tissues at the age of 2 months." (PMID 27344183, 2016).
tumor (continued). "Immunoprecipitation analyses verified the expression and citrullination of ENO1, HSP60, KRT8, and TUBB in the total protein lysates of the tumour cell lines." (PMID 24099319, 2013). "ENO1, HSP60, KRT8, PDI, TCRβ, TUΒΒ, and VIME were identified in the tumour cell lines using 2-D WB, and immunoprecipitation verified that ENO1, HSP60, KRT8, and TUBB were expressed and citrullinated in these cell lines." (PMID 24099319, 2013). "The current study identified novel citrullinated proteins, including ENO1, HSP60, KRT8, and TUBB, in tumour cells." (PMID 24099319, 2013). "Phenotypes underlying such clustering patterns showed that CTCs maintained higher expression than all tumor cell lines for FOXC1, KRT18, PTEN, NPTN, TGFß1, KRT8, ZEB2, and CXCR4." (PMID 22586443, 2012). "Reverse transcription-quantitative polymerase chain reaction validation results demonstrated that KRT8 and S100A16 were significantly upregulated in tumor tissues, while COL4A3 and SMAD9 expression was downregulated, which was consistent with the TCGA-LUAD database analysis." (PMID 41239716, 2025). "Moreover, gene expression analysis showed that the expressions of KRT8 and S100A16 were significantly increased in tumor tissues, while the expressions of COL4A3, SMAD9, MAP3K8 and CCDC146 were decreased." (PMID 41239716, 2025). "To identify the extent of transcriptome remodeling in HCs from tumors (THC), we extracted the tumor fraction and compared the gene expression profile of THC with tumor epithelial cells (EPCAM+ and KRT8+) and THCs with tumor-associated macrophage/monocyte cells (CD14+ and CD163+)." (PMID 38611120, 2024). "Thus, EPCAMhigh tumor spots more often demonstrated the expression of such epithelial markers as KRT7, KRT8, and KRT18 compared to EPCAMlow and EPCAM-negative clusters." (PMID 39456890, 2024). "However, in agreement with feature plots, GPx2 KD tumours harboured areas expressing both E and M markers involving KRT14 (basal) and KRT8 (luminal) relative to control tumours expressing only KRT8 (Areas 1, 3, 4)." (PMID 38238426, 2024). "It is conceivable that keratin 8 molecules on lung tumor cell surface are recognized by specific antibodies generated by ESC-based vaccine, resulting in recruitment of effector immune cells and subsequent tumor cell apoptosis." (PMID 39739089, 2024). "Moreover, p63 was mostly co-localised with KRT8 and KRT14 in GPx2KD tumours and this pattern was recapitulated in distant mets." (PMID 38238426, 2024). "Multiplex immunofluorescence in additional prostatectomy and patient tumor specimens further confirmed the KRT8+/AR+ normal epithelial cells to have no detectable expression of NSD2, which was robustly expressed in the transformed epithelial cells." (PMID 39251788, 2024). "Namely, PyMT2/GPx2OE tumours were negative for KRT8/KRT14/pAMPK/GLUT1 as compared to control tumours which were KRT8/pAMPK positive." (PMID 38238426, 2024). "After excluding potential low‐quality cells and removing a cluster with high expression of epithelial markers (such as EPCAM, KRT8, KRT19) to distinguish fibroblasts from tumour cells undergoing epithelial‐mesenchymal transition (EMT), 13 subclusters of fibroblasts were retained." (PMID 38115703, 2023). "Similar to the patients’ SARC tumor component and in contrast to the UroCa component, organoids were negative for additional epithelial markers (KRT5, KRT8), yet showed a strong expression of Vimentin, hallmark of mesenchymal-like cells." (PMID 37919480, 2023). "Cytokeratin profiling of control and Kmt2c null tumours showed lack of Keratin 5 (Krt5) and maintenance of Keratin 8 abundance (Krt8)." (PMID 36933062, 2023). "Besides, we performed flow cytometry experiments for fresh tumor tissues from an MBC patient to validate and quantify CD3 + KRT8+ double-positive T cells." (PMID 37696831, 2023).
tumor (continued). "Tumors were harvested from two Krt8-CreERT/Rosa26-mTmG /MMTV-PyMT mice and sorted by flow cytometry for all GFP-expressing cells to specifically analyze both luminal- and basal-like tumor cells of luminal origin." (PMID 36859337, 2023). "Besides the differential expression of KRT5 and KRT19 between the margin and tumor center, KRT6B, KRT8, KRT10, and KRT17 were identified among the proteins differentiating the cancer from control tissue." (PMID 35512017, 2022). "KRT8 and KRT18 were commonly expressed in the three tumor cell subtypes." (PMID 35494058, 2022). "Compared with tumor cells at the primary site, metastatic tumor cells still retained high expressions of KRT8 and KRT18, whereas metastatic tumor cells no longer expressed MMRN1, PROX1, TCF7L1, SCG3 and SV2C." (PMID 35494058, 2022). "Xenograft tumor of HCT 116 showed an increased expression of neuronal genes MAP2 and SYN1, neural stemness genes CDH2, MSI1, NCAM1, SOX2/9, VIM and ZEB2, and genes for mesodermal and endodermal tissues (ACP5, AFP, DESMIN, HNF4A and KRT8)." (PMID 33468253, 2021). "Soluble protein fragments of keratins, including KRT7, KRT8, KRT18 and KRT19, can be detected in the circulation of cancer patients and are used to monitor disease progression and patient prognostic in certain tumour types." (PMID 34070214, 2021). "In conclusion, our results provide new evidence to support the idea that KRT8 expression levels were significantly higher in metastatic ccRCC tumor tissues than in non-metastatic ccRCC tumor tissues." (PMID 29100303, 2017). "GA inhibited tumor cell proliferation in a concentration- and time- dependent manner while nontumorigenic luminal epithelial cells derived from a normal C57BL/6 prostate (B6WT, KRT8+/ARlow >80%, KRT8+/KRT5+ <20%) were relatively resistant to GA." (PMID 29100379, 2017). "KRT8 mRNA and protein levels were significantly higher in VTT tissues than in corresponding tumor or peritumoral tissues, suggesting that KRT8 may play an oncogenic role in ccRCC progression." (PMID 29100303, 2017). "Since Cyp19-Cre is not expressed in the ovarian surface epithelium, our data suggest that overactivation of TGFBR1 in ovarian surface epithelial cells is not required for the observed KRT8 expression in tumor tissues." (PMID 27344183, 2016). "Double immunofluorescence revealed low expression or absence of INHA in KRT8-positive cells within tumor lobules, suggesting distinct identity of KRT-positive cells." (PMID 27344183, 2016). "In another study, primary mouse keratinocytes were transduced with the Smad7 gene resulting in enhanced keratinocyte proliferation, blocked normal differentiation, and induced keratin 8, a marker of malignant conversion, but did not result in tumor formation." (PMID 24047375, 2013). "As expected, the HPCa57 patient tumor exhibited typical GS7 histology with crowded tumor glands, in which most cells stained positive for prostate luminal epithelial cell markers PSA, nuclear AR, and cytokeratin 8 (CK8)." (PMID 23451107, 2013). "Notably, tumor characterization in these models revealed three distinct tumor types in Ad-K8-Cre-injected mice (i.e., Type 1: KRT8+KRT14− luminal tumor cells surrounded by KRT14+KRT8− basal tumor cells; Type 2: KRT8/KRT14 double-positive; Type 3: KRT8+KRT14− luminal only)." (PMID 40622584, 2025). "We validated that H3K27ac/H3K4me3 activity at the KRT5 and KRT8/18 loci served as an accurate indicator of epithelial identity and that snCUT&RUN can be used to comprehensively analyze a mixture of samples to infer epithelial changes and the accompanying TF motif changes during tumor progression." (PMID 39622638, 2025). "Indeed, echinomycin-treated GPx2 KD tumours were negative for GLUT1, pAMPK and KRT14 but retained KRT8 expression relative to vehicle-treated GPx2 KD tumours which were positive for all four markers." (PMID 38238426, 2024).
tumor (continued). "Additionally, calculation of tumour‐related epithelial markers (EPCAM, KRT8 and KRT19) for each spot in all samples revealed that tumour areas showed the highest epithelial scores compared to other areas, confirming the accurate identification of tumour areas." (PMID 39187937, 2024). "Besides, LAMC2, KRT8 and KRT19 spatially patterned tumor markers shared ‘epidermis development’ and ‘cellular component morphogenesis’ spatially patterned pathways in the tumor region, which may indicate the proliferation of cancer cells." (PMID 36243975, 2023). "We also found LAMC2, KRT8 and KRT19 spatially patterned tumor markers sharing ‘epidermis development’ and ‘cellular component morphogenesis’ spatially patterned pathways in the tumor region, which may indicate the proliferation of cancer cells." (PMID 36243975, 2023). "In addition, keratin 8 (KRT8), heat shock protein 60 (HSP60), α-enolase (ENO1), tubulin β (TUBB), T cell receptor β chain (TCRβ) and vimentin (VIME) are also suggested to be citrullinated proteins in tumor cells." (PMID 37777749, 2023). "Interestingly, most of the cells co-expressing GFP and Krt14 also co-expressed Krt8, suggesting that these tumor cells do not completely lose their luminal identity, but instead gain a lumino-basal phenotype." (PMID 36859337, 2023). "Furthermore, we also found KRT8, a marker of normal Merkel cells and MCC, coexpressed in single cells with higher levels of WWTR1 (center) indicating that these WWTR1-expressing cells probably represented MCC tumor cells." (PMID 36719743, 2023). "Interestingly, when the same oncogenic hit was overexpressed in LCs (Krt8-expressing cells) or BCs (Lgr5-expressing cells), the resulting tumors were basal-like, HER2-positive, and luminal B (Krt8-derived tumor), or mainly luminal A and B (Lgr5-derived tumors)." (PMID 35052683, 2021). "For Wnt1-EarlyEx tumors, these two fractions accounted for only about 65% of the tumor, with the remaining 35% consisting of regions/cells that did not stain positive for either Krt5 or Krt8/18; the identify of these non-staining cell type(s) is unknown." (PMID 31213486, 2019). "In the Krt8-CreERT2 model luminal tumor cells lacking Pten and Tgfbr2 de-differentiate to dual positive cells, a process that may be of interest for understanding human CaP progression." (PMID 29782499, 2018). "Interestingly, while some tumor cells in the metastatic lesions of SKO cells still retained keratin 5 (CK5), an undifferentiated marker of basal lineage, some cells in these lesions activated expression of keratin 8 (CK8), a marker of luminal cells." (PMID 30038266, 2018). "In addition to these changes, in the serum-depleted proteome we observed downregulation of keratin 8, and upregulation of vimentin, the glycolytic enzymes enolase and pyruvate kinase (PKM2) and tumor progression-related inosine-5’-monophosphate dehydrogenase 2 (IMPDH2) enzyme." (PMID 28536624, 2016). "Thus, the concept of a non-mechanical role for KRT8 in ATC tumor etiology is not without precedent." (PMID 29443941, 2018). "While TKO tumor cells were primarily NE (ASCL1+), TKO-Nicd1 organoid tumor cells were non-NE and expressed markers of prostate epithelium (Krt5+, Krt8+, Hes1+)." (PMID 39024561, 2024). "We successfully grew tumor chunks from new PDX line LTL706B in mouse renal capsules and then confirmed immunopositivity for PCa markers (AR, KRT8, and PSMA) and absence of CDK12." (PMID 39368479, 2024). "Exceptional responders to therapy exhibit increased RNA abundance of KRT8 and KRT18 relative to nonresponders to therapy, consistent with exceptional responders to therapy having tumours with luminal features." (PMID 38049604, 2023). "Notably, canonical breast cell differentiation genes and molecular markers (KRT8, KRT18, KRT14, TP63, ERBB2, ESR1, PGR) were not differentially expressed, suggesting the cells maintain their differentiation state and tumor subtype." (PMID 34741115, 2021).
tumor (continued). "Quantification of these phenotypes within the tumor show that about 90% of the basal marker and GFP co-expressing cells were of the lumino-basal phenotype (mean = 89.10%), with only about 10% of cells transitioning to a fully basal phenotype without Krt8 co-expression (mean = 10.90%)." (PMID 36859337, 2023).
cancer (187 papers, 1996 to 2025). A tumor composed of atypical neoplastic, often pleomorphic cells that invade other tissues. "Genomic and transcriptomic analysis of >5000 patients demonstrates that KRT8 mutation and copy number amplification are frequently evident in epithelial-derived cancers." (PMID 29443941, 2018). "KRT8 expression on the surface of cancer cells has been associated with enhanced adhesion to fibronectin and the extracellular matrix." (PMID 26398185, 2015). "We propose, therefore, that KRT8 is not only a diagnostic cancer biomarker, but also may be involved in ATC cell survival." (PMID 29443941, 2018). "Recent studies have indicated that keratin 8/18 loss can promote cancer cell migration." (PMID 25973684, 2015). "This analysis highlights distinct expression patterns for CPM and KRT8, suggesting their potential roles as biomarkers across various cancers." (PMID 40136513, 2025). "Both AC1 and AC2 showed high levels of luminal epithelial cell marker Krt8, indicating they are cancer cell clusters." (PMID 40394007, 2025). "Based on this observation, we examined the expression profile of Arg1 and HIF1a by mIF imaging in the same ROIs employed for the analysis of the colocalization of Krt8+ cancer cells, CD31+ vasculature, and Col1 1+ protein fibers." (PMID 39372930, 2024). "Upon ERG activation, BasalLum cells give rise to the highly proliferative intermediate state, which subsequently transitions to the larger population of Krt8+ luminal cells characteristic of ERG-positive human cancers." (PMID 38585869, 2024). "Among the upregulated genes we noticed markers those were associated with cancer genesis and development, including SOX4, SPINK1, CEACAM6, KRT8 and KRT18." (PMID 37957625, 2023). "Keratin 8 (KRT8) plays an essential role in the development and metastasis of several human cancers." (PMID 36672349, 2023). "Among these three cell types, HPCs population contained mainly cancer cells, as KRT8 and KRT18 were the marker genes of epithelial cells." (PMID 37517066, 2023). "KRT8 (keratin 8), a type II basic intermediate filament protein, is essential for the development and metastasis of various cancers, including LUAD." (PMID 35711913, 2022). "The results from TCGA indicated that the expression of KRT8 was significantly higher in cancer tissues compared to normal tissues (P < 0.001), which is similar with the results from the GSE116959 database (P < 0.001)." (PMID 35664775, 2022). "Consistently, the protein expression of KRT8 was obviously upregulated in cancer tissues compared to paired normal tissues." (PMID 35664775, 2022). "That CXCL12 is cross-linked to KRT19 allows the heterodimer to self-assemble with KRT8, which is also secreted, into a higher-order filamentous network that coats the cancer cell." (PMID 35046049, 2022). "KRT7 was also positively correlated with keratin-8 (KRT8) expression in an intra-cellular gene-gene correlation, with KRT8 having been identified as a pan-cancer early biomarker in a multi-scale integrated analysis." (PMID 35406395, 2022). "We chose these peptides because these genes, such as Annexin 2, Calprotectin A8, Calprotectin A9, Keratin 19, Keratin 8, Angiopoietin-1, Tissue inhibitor of metalloproteinase (TIMP), and Afamin, are associated with cancer progression." (PMID 36672532, 2022). "Analysis of DNA methylation profiles of 9855 samples across 23 cancers from The Cancer Genome Atlas (TCGA) revealed KRT8 to be the most significantly hypo-methylated gene across all cancers." (PMID 35204653, 2022). "Cancer cells were characterized by strong expression of canonical mammary epithelial cell markers, Epcam and Cd24, and including luminal markers Krt8 and Krt18, consistent with the luminal progenitor nature of MMTV‐PyMT tumors." (PMID 35611998, 2022). "KRT15, KRT19 and KRT8 were amplified and the expression were significiantly higher in the AA cancer cell lines compared to EA cell lines." (PMID 36033462, 2022).